BMPR2 (bone morphogenetic protein receptor type 2)
Diseases named in the same sentence as BMPR2 in open-access papers (continued):
Sharing a sentence is not in itself a finding about the gene and the disease.
BMPR2 also shares sentences with these, for which no sentence is quoted: asthma (3 papers); bladder cancer (3); Pulmonary capillary hemangiomatosis (3); Arrhythmia (2); benign ovarian tumors (2); cardiac arrhythmia (2); cerebral cavernous malformation (2); chronic lung disease (2); chronic thromboembolic pulmonary hypertension (2); essential hypertension (2); interstitial lung disease (2); melanoma (2); osteoporosis (2); renal cell carcinoma (2); rheumatoid arthritis (2); schistosomiasis (2); secondary pulmonary hypertension (2); squamous cell carcinoma (2); valvular heart disease (2); acute chest syndrome (1); allergic disease (1); and glucocorticoid deficiency (1); anemia (1); Anxiety (1); arteriovenous malformations (1); Arthritis (1); atopic asthma (1); Barrett's oesophagus (1); basal cell carcinoma (1); CADASIL (1).
A further 61 diseases each share a sentence with BMPR2 in 1 paper.